LINC02875 (long independently transcribed non-coding RNA 2875)
Synonyms: C17orf82
Gene: Long non-coding RNA gene on chromosome 17 (61,411,751 to 61,413,280, forward strand). Ensembl gene ENSG00000187013.
Diseases named in the same sentence as LINC02875 in open-access papers:
LINC02875 is named in the same sentence as 7 diseases in open-access papers, as found by Europe PMC text mining. Sharing a sentence is not in itself a finding about the gene and the disease. The quoted sentences say what the papers report.
glioma (2 papers, 2021 to 2022). A benign or malignant brain and spinal cord tumor that arises from glial cells (astrocytes, oligodendrocytes, ependymal cells). "Therefore, we used Smart Silencer to silence the expression of PCBP1-AS1 and LINC02875 in glioma cells." (PMID 33828990, 2021). "The RT-PCR assay was used to analyze the expression levels of PCBP1-AS1 and LINC02875 in different glioma cell lines, and the results showed that the PCBP1-AS1 and LINC02875 expression levels were relatively high in LN18 and T98G glioma cells." (PMID 33828990, 2021).
LINC02875 also shares sentences with these, for which no sentence is quoted: breast carcinoma (2 papers); chronic kidney disease (1); colorectal cancer (1); head and neck squamous cell carcinoma (1); Hypertension (1); ischemic stroke (1).